TRH (thyrotropin releasing hormone)
Diseases named in the same sentence as TRH in open-access papers (continued):
Sharing a sentence is not in itself a finding about the gene and the disease.
Anorexia (8 papers, 2017 to 2026). Lack of desire to eat (loss of appetite). "Rats subjected to dehydration-induced anorexia (DIA) model show increased PVN TRH mRNA expression, associated with their decreased food intake." (PMID 35545425, 2022). "Rikkunshito attenuated anorexia and weight loss by upregulating hypothalamic orexigenic NPY and decreasing TRH." (PMID 32906727, 2020). "Rikkunshito was demonstrated to ameliorate anorexia and weight loss by upregulating hypothalamic orexigenic neuropeptide Y (NPY) and decreasing thyrotropin-releasing hormone (TRH) in paraventricular nucleus (PVN)." (PMID 32906727, 2020). "In contrast, other authors show that TRH injection into the LH induces anorexia in rats." (PMID 38921437, 2024). "For example, the peripheral administration of TRH produces anorexia, an effect that is likely central since TRH administration into the cerebrospinal fluid or directly into the hypothalamus has a rapid, potent anorexigenic effect that is independent of thyroid function." (PMID 35934753, 2022). "Association between high TRH release with activation of its mRNA expression is assumed after observing the coordination of those processes in PVN TRHergic neurons by stimuli, such as suction in lactating rats, cold and dehydration-induced anorexia." (PMID 29057835, 2017). "Taken together, this reduction in TRH gene expression in the PVN in cachectic rats by RKT may be partly involved in the amelioration of anorexia-cachexia by RKT." (PMID 28249026, 2017). "Optogenetic stimulation of GLP-1R–expressing TRH-positive neurons in the ARC also suppressed feeding via AgRP neuron inhibition, and AgRP neuron stimulation partially overcame Ex-4 or TRH-neuron stimulation–induced anorexia." (PMID 41542773, 2026). "That hypothesis is in agreement with studies showing that an incoming CRH is increasing PVN TRH mRNA levels, given that the blockade of CRH-R2 in the PVN attenuates TRH expression and the anorexia of DIA animals." (PMID 35545425, 2022).
Anxiety (8 papers, 2015 to 2024). Intense feelings of nervousness, tension, or panic often arise in response to interpersonal stresses. "The anxiety levels of the experimental groups resulted to be negatively associated with TRH expression, which supported its anxiolytic role." (PMID 38892044, 2024). "As the amygdalar thyrotropin-releasing hormone (TRH) is believed to have anxiolytic properties, we evaluated its expression changes in association with anxiety levels." (PMID 38892044, 2024). "Trhr encodes the receptor for thyrotropin-releasing hormone (TRH); TRH-R1 knockout mice exhibited increased anxiety- and depressive-like behaviors." (PMID 34276303, 2021). "Clinical studies, although scarce, also show that patients with anxiety present lower TRH cerebrospinal levels than the controls." (PMID 38892044, 2024). "In rodents, inhibition of Pde7 regulates anxiety behaviors, mediated by increasing levels of hypothalamic thyrotropin-releasing hormone." (PMID 30705647, 2018). "Therefore, we focused on the analysis of a BLA-regulated behavior such as anxiety and on the expression of TRH as an indicator of BLA neuronal activity." (PMID 38892044, 2024). "Although research on TRH-DE, which is responsible for deactivating the release of the thyrotropin-releasing hormone (TRH) in humans, is sparse, a recent study in rats supports the participation of TRH during response to anxiety provoking situations." (PMID 26111525, 2015). "TRH-(thyrotropin-releasing hormone)-ergic valop-expressing neurons in the Edinger–Westphal nucleus might mediate a light-dependent eye response; while serotonergic valop-expressing neurons in the superior raphe could regulate anxiety-like behavior depending on ambient light conditions." (PMID 27199680, 2016). "Also, it is interesting that the role of TRH in mood has been observed both in the instinctive responses to adverse stimuli after a rise in CORT and in learned anxiety processes of recognizing fearful elements in novel environments." (PMID 38892044, 2024).
diabetes (8 papers, 2015 to 2025). "For instance, “TSH to thyrotropin-releasing hormone response” has been found to be reduced in diabetes, causing accompanying decreased T3 levels and hypothyroidism." (PMID 35106234, 2021). "Type 2 diabetes mellitus has been proven to be negatively correlated with serum TSH38 levels, and it has been shown that poorly controlled diabetes removed the nocturnal TSH peak because the TSH response to TRH was disturbed." (PMID 38982986, 2024). "Potential mechanistic links include shared autoimmune pathogenesis, hyperglycemia-induced alterations in the hypothalamic-pituitary-thyroid axis (e.g., reduced deiodinase activity and altered T3/reverse triiodothyronine (rT3) levels), and impaired TSH response to TRH in poorly controlled diabetes." (PMID 41306154, 2025). "Researchers believed that diabetes mellitus could affect thyroid function by altering TRH and TSH levels." (PMID 34092241, 2021). "Finally, multiple studies have suggested that TRH acted as a regulator of homeostasis involving immune and endocrine system, whereas imbalance of inflammation or diabetes plays a recognized role in neurodegenerative diseases like PD or AD." (PMID 30618632, 2018). "In euthyroid individuals with diabetes mellitus, the serum T3 levels, basal thyroid-stimulating hormone (TSH) levels, and TSH response to thyrotropin-releasing hormone (TRH) may all be influenced by glycemic status." (PMID 39583465, 2024). "Hyperinsulinemia was also prevalent in T2DM population and insulin might influence thyrotropin releasing hormone (TRH) and TSH when modulating glycemic status, thus, diabetics might have higher TSH." (PMID 26270348, 2015).
Hypertension (7 papers, 2016 to 2024). The presence of chronic increased pressure in the systemic arterial system. "Studies showed that diabetes mellitus, history of cardiovascular disease, longer hypertension duration, left ventricular hypertrophy, heart failure glomerular filtration rate and black race had been significantly associated with TRH." (PMID 32343723, 2020). "Interestingly, activation of the TRH system, with increased production of TRH and an upregulation of its receptors has also been implicated in the pathogenesis of hypertension." (PMID 31010095, 2019). "Activation of the RAS, or Ang-II itself, also seems to be involved in the effects of TRH on central cardiovascular regulation, being key in the etiology of hypertension." (PMID 34836194, 2021). "Meticulous emphasis should be placed on to detect the prevalence of true hypertension resistance and future studies should discover the impact of aggressive antihypertensive medications scale up on the risks of TRH." (PMID 32343723, 2020). "TRH has become a threaten for health care professionals in management of hypertension, prevention of hypertension related complications, control of BP, and it increased cardiovascular risks and premature death remarkably." (PMID 32343723, 2020). "Great emphasis should be rendered to estimate true hypertension resistance prevalence and future studies should descry the effect of aggressive antihypertensive medications escalation on the risks of TRH." (PMID 32343723, 2020). "Furthermore, BMI greater than 30kg/m2 and six years and longer duration of hypertension were the factors which predicted TRH." (PMID 32343723, 2020). "Nephrologists and hypertension specialists tend to think that true TRH is a very rare condition." (PMID 27375498, 2016).
acromegaly (6 papers, 2013 to 2024). Acromegaly is an acquired disorder related to excessive production of growth hormone (GH) and characterized by progressive somatic disfigurement (mainly involving the face and extremities) and systemic manifestations. "Acromegaly with prolactin-cosecreting pituitary tumors has been found to have a mammotroph-like phenotype, such as a paradoxical GH response to TRH loading and dopamine agonist effectiveness." (PMID 38954291, 2024). "It has been reported that bromocriptine was more effective in acromegaly patients with an increased GH response to TRH loading alone than in those with an increased GH response to both TRH and LHRH loading." (PMID 38954291, 2024). "We previously showed the clinical characteristics of acromegaly with a paradoxical growth hormone (GH) response to oral glucose or thyrotropin-releasing hormone." (PMID 38954291, 2024). "This test has been used in the diagnosis of acromegaly, where a paradoxical response, defined as peak to basal GH ratio > 2 during a standard 200 μg TRH test, is observed in 50% to 75% cases." (PMID 31650157, 2020). "We previously reported the clinical characteristics including the efficacy of first-generation somatostatin ligand (fg-SRL) in acromegaly patients with an increased growth hormone (GH) response to the oral glucose tolerance test (OGTT) or thyrotropin-releasing hormone (TRH) loading." (PMID 38954291, 2024). "In addition to OGTT and TRH loading, luteinizing hormone-releasing hormone (LHRH) loading induces an increased GH response in some acromegaly patients (LHRH responders)." (PMID 38954291, 2024).
adenoma (6 papers, 2013 to 2025). A neoplasm arising from the epithelium. "Tumor 8, a silent plurihormonal adenoma, responded exclusively and intensely to TRH/DA, suggesting a predominant lactotroph phenotype-like differentiation." (PMID 38612778, 2024). "Of the three “silent” adenomas, tumor 1, a silent GH adenoma, responded predominantly to GHRH and to a lesser extent to GnRH and TRH, whereas tumor 13, a silent ACTH adenoma, responded similarly to GHRH, CRH, TRH, and TRH/DA." (PMID 38612778, 2024). "Other NFPAs contained polyhormonal gonadotropes responding to LHRH and TRH (type II non-functioning adenomas) or monohormonal corticotropes lacking responses to HRHs (type I non-functioning adenomas)." (PMID 26106585, 2015). "Regarding NFPAS, we found that a large fraction of NFPAs studied were made of cells holding a very particular phenotype: These cells are rather homogenous, store no detectable hormone (null cells) and responded only to TRH (type III non-functioning adenomas)." (PMID 26106585, 2015). "Furthermore, in normal pituitary cells as in adenoma, endogenous TRH and TRH receptors (TRHR) were documented not only in thyrotroph but also in somatotroph cells." (PMID 38650008, 2024). "The majority of such adenomas are characterized by autonomous secretion of TSH, which neither responds to TRH nor is suppressed by increasing doses of administered T3 or T4." (PMID 27774323, 2016). "The other two previously reported adenomas were made of cells storing no hormone or mostly ACTH and showing responses to CRH and TRH and to a lesser extent to GHRH suggesting a corticotrope ontogeny." (PMID 26106585, 2015).
hypercortisolemia (6 papers, 2018 to 2024). "It was proposed that hypercortisolemia decreases TRH mRNA levels and glucocorticoid administration decreases TSH secretion as well as TRH-induced TSH stimulation." (PMID 34635736, 2021). "One study reported that hypercortisolism could lower hypothalamic TRH expression and lead to TSH suppression." (PMID 35743974, 2022). "TSH suppression in hypercortisolemia is most likely related to decreased TRH gene expression." (PMID 29641732, 2018). "This study investigated the effect of TRH administration on circulating concentrations of ACTH and cortisol, in both clinically normal control dogs and dogs with PDH, in order to evaluate whether a TRH stimulation test may be used to diagnose hypercortisolism in dogs." (PMID 30362899, 2018). "Furthermore, many studies have indicated that hypercortisolemia blunts the TSH response to TRH." (PMID 29641732, 2018). "Both thyrotropin-releasing hormone (TRH) and thyroid-stimulating hormone (TSH) release, as well as the deiodinase activity, have been shown to be altered by hypercortisolism." (PMID 33808529, 2021). "TSH response after TRH stimulation is impaired in endogenous hypercortisolism, in which the increase of TSH after TRH stimulation is significantly lower in CS patients than in healthy subjects." (PMID 33808529, 2021).
Hypoglycemia (6 papers, 2014 to 2025). A decreased concentration of glucose in the blood. "Because of the risk of hypoglycemia in this patient, a thyrotropin-releasing hormone (TRH) stimulation test for TSH was the only stimulatory test performed." (PMID 25182385, 2014). "These two hormones (PRL and GH) have partly the same common secretory mechanisms, such as estrogens, dopamine, TRH, ghrelin, stress or hypoglycemia." (PMID 41155234, 2025). "In conditions with a clinical suspicion of PGCR, resistance can also be observed by the typical response of serum thyroid-stimulating hormone (TSH) to thyrotropin-releasing hormone (TRH) administration and/or the growth hormone response to insulin-induced hypoglycemia." (PMID 38812815, 2024).
thyrotoxicosis (6 papers, 2009 to 2024). A hypermetabolic syndrome caused by the elevation of thyroid hormone levels in the serum. "Further exploration of TRH’s role in seizure management within the context of thyrotoxicosis merits ongoing investigation." (PMID 38413695, 2024). "In GD, where the TRH is typically reduced and thyroid overstimulation results in thyrotoxicosis, the dopamine system would be overall inhibited." (PMID 39070061, 2024). "Notably, thyrotropin-releasing hormone (TRH) has emerged as a potential therapeutic target for managing seizures in thyrotoxicosis." (PMID 38413695, 2024). "We set out to study whether increased hypothalamic T3 availability could reflect local thyrotoxicosis and explain feedback inhibition-induced suppression of the TRH gene in the context of the low T3 syndrome in prolonged critical illness." (PMID 19747372, 2009). "This is compatible with the recent report comparing Pax8-null mice with Pax8/TRH-R1 double knockout mice and the previous study that administration of TRH failed to stimulate TSHβ synthesis in a subject with overt thyrotoxicosis." (PMID 21533184, 2011).
autoimmune thyroid disease (5 papers, 2011 to 2025). Inflammatory disease of the thyroid gland due to autoimmune responses leading to lymphocytic infiltration of the gland. "We conducted a bidirectional two-sample Mendelian randomization (MR) analysis to investigate the causal association between PSC and TD, such as autoimmune thyroid disease (AITD), thyroid cancer (TC), thyroid stimulating hormone (TSH), thyrotropin-releasing hormone (TRH), among others." (PMID 37928559, 2023).
cognitive deficits (5 papers, 2011 to 2024). "One theory is that the organic brain diseases causing cognitive impairment also reduce TRH secretion from hypothalamus and other brain areas." (PMID 24171118, 2013). "Administration of TRH to senescence-accelerated mice, fimbria-fornix lesioned rats, and AD patients was reported to ameliorate cognitive defects." (PMID 23437202, 2013). "In individuals with cognitive impairment, such as MCI and AD dementia, the neurodegeneration caused by AD process could potentially decrease the secretion of thyrotropin releasing hormone (TRH) and TSH, subsequently reducing the levels of thyroid hormones." (PMID 39044293, 2024). "In vivo, TRH, or some analogs, activate the septo-hippocampal and basalis cortical cholinergic systems, eliciting acetylcholine release onto the hippocampus and cortex and restore cognitive deficits of animals with lesions in the medial septum." (PMID 32457627, 2020).
panhypopituitarism (5 papers, 2020 to 2024). Insufficient production of all the anterior pituitary hormones. "Only recently have new cutoff values been suggested for men and women via the TRH stimulation test, which assesses PRL responses at 20 and 60 min after IV administration of 200 μg TRH in 48 patients with panhypopituitarism and 20 healthy controls." (PMID 39425884, 2024). "In patients with panhypopituitarism, the peak prolactin responses to TRH were significantly lower than healthy controls." (PMID 39037546, 2024). "Free T3, TSH, PRL and PRL responses to TRH stimulation were lower in patients with panhypopituitarism compared to the control group." (PMID 38700812, 2024). "Load tests were conducted using four hypothalamic hormones: LH-releasing hormone (100 μg), GH-releasing hormone (100 μg), corticotropin-releasing hormone (CRH, 100 μg), and thyrotropin-releasing hormone (TRH, 250 μg) in order to confirm the diagnosis of panhypopituitarism." (PMID 33019443, 2020).
Parkinson disease (5 papers, 2010 to 2023). A progressive degenerative disorder of the central nervous system characterized by loss of dopamine producing neurons in the substantia nigra and the presence of Lewy bodies in the substantia nigra and locus coeruleus. "There is growing evidence that TRH can be implicated in neurodegenerative diseases of aging, such as Alzheimer’s disease and Parkinson’s disease." (PMID 36147745, 2022). "TRH can be implicated in neurodegenerative diseases associated with aging, including Alzheimer’s disease and Parkinson’s disease." (PMID 35563779, 2022). "Our finding of a dramatic and selective up-regulation of TRH expression in the sensorimotor striatum of dyskinetic rat models suggests a TRH-mediated regulatory mechanism that may underlie the pathologic neuroplasticity driving dopamine hyper-responsivity in Parkinson's disease." (PMID 21085660, 2010). ".TRH is used to treat brain and spinal cord injuries as well as CNS diseases, including epilepsy, schizophrenia, spinal cord trauma, Alzheimer’s disease (AD), Parkinson’s disease (PD), and depression." (PMID 38111381, 2023). "Our findings suggest that up-regulation of striatal expression of TRH in the striatum and its output pathways is strongly correlated with the expression of L-DOPA induced dyskinesia and that this up-regulation could be an essential feature of the dyskinetic state in parkinsonism." (PMID 21085660, 2010).
pituitary apoplexy (5 papers, 2012 to 2024). A rare, potentially life-threatening disorder caused by acute ischemic infarction or hemorrhage in the pituitary gland. "The TRH test to confirm TSH secretory capacity carries the risk of pituitary apoplexy, so caution is required in patients with pituitary tumors." (PMID 37484278, 2023). "TRH (26 cases, 76.4%) and LH-RH (23 cases, 67.6%) were the hormonal stimulants most commonly associated with the elicitation of pituitary apoplexy." (PMID 22934202, 2012). "Although the precise mechanisms of pituitary apoplexy associated with TRH- and LH-RH stimulation remain unclear, it has been suggested that TRH elevates the serum level of norepinephrine, and that vasospasm or pressor effects may be precipitating factors." (PMID 22934202, 2012). "TRH stimulation has been reported to lead to pituitary apoplexy in seldom cases which is thought to be due to its possible vasoconstrictive effects." (PMID 39037546, 2024). "There were only mild and reversible adverse effects related to the TRH test except for possibly one case (0.3%) experiencing a pituitary apoplexy." (PMID 37850100, 2023). "One patient (0.3%) experienced a serious side effect consisting of a pituitary apoplexy in relation to the TRH test accompanied by a SAT." (PMID 37850100, 2023).
pituitary tumor (5 papers, 2013 to 2024). A benign or malignant neoplasm affecting the pituitary gland. "Additional studies with a larger number of patients are warranted to provide better understanding of the basic characteristics of responsiveness to TRH during the TST in patients with GH-producing pituitary tumors." (PMID 24348552, 2013). "Freshly dispersed pituitary tumor cells were cultured for a few hours and then loaded with fura-2/AM and subjected to calcium imaging to monitor Ca2+ responses induced by the four classic HRHs perfused sequentially (CRH, LHRH, TRH, and GHRH)." (PMID 26106585, 2015).